LINC02308 (long independently transcribed non-coding RNA 2308)
Gene: Long non-coding RNA gene on chromosome 14 (81,441,206 to 81,450,377, reverse strand). Ensembl gene ENSG00000258675.
Diseases named in the same sentence as LINC02308 in open-access papers:
LINC02308 is named in the same sentence as 1 disease in open-access papers, as found by Europe PMC text mining. Sharing a sentence is not in itself a finding about the gene and the disease. The quoted sentences say what the papers report.
glioma (1 paper, 2023). A benign or malignant brain and spinal cord tumor that arises from glial cells (astrocytes, oligodendrocytes, ependymal cells). "LINC02308 was significantly overexpressed in glioma and acts as a sponge to express miR-30e-3p to up-regulate TM4SF1 and promote glioma occurrence." (PMID 36869083, 2023).